BECN1 (beclin 1)
Diseases named in the same sentence as BECN1 in open-access papers (continued):
Sharing a sentence is not in itself a finding about the gene and the disease.
breast tumors (26 papers, 2010 to 2025). "Loss of heterozygosity was detected in more than 45% of the breast tumors, and a dense cluster of CpG islands was found from the 5' end to the intron 2 of the beclin 1 gene." (PMID 20230646, 2010). "Meanwhile, allelic loss of beclin 1 was only found in a portion of the breast tumors with down-regulated expression, indicating that mechanisms other than allelic deletion may be responsible for the decrased mRNA expression." (PMID 20230646, 2010). "Improved HED delivery into breast tumors and enhanced its anti‐tumor efficacy by promoting mitochondria‐mediated cell apoptosis and autophagy via upregulation of Beclin‐1 and LC3‐II." (PMID 40529859, 2025). "The removal of the BECN1 gene (Beclin-1) increases the likelihood of postpartum breast tumor occurrence." (PMID 38338839, 2024). "Beclin-1 expression inversely correlates with Akt and extracellular regulated kinase 1/2 (ERK) phosphorylation in human breast tumors through its Beclin-1-dependent regulation of insulin-like growth factor-1 (IGF-1) and EGF receptor trafficking." (PMID 35309939, 2022). "Autophagy decreases the proliferation of MCF-7 breast tumor cells overexpressing Beclin-1, as well as the incidence of spontaneous tumors in Beclin-1-haplodeficient mice." (PMID 32707662, 2020). "The expression levels of Beclin-1, an autophagic mediator which is deleted in 50% of breast tumors, were modestly but clearly upregulated in the cells treated with Tetra alone, but not by AsIII alone." (PMID 30123091, 2018). "Inactivation of autophagy-related genes, such as Beclin-1, leads to increased tumorigenesis in mice while overexpression of these genes (Beclin-1, Atg5) inhibit the formation of human breast tumors in mouse models." (PMID 28536348, 2017). "Inactivation of autophagy-related genes, such as Beclin-1, leads to increased tumorigenesis in mice while the overexpression of these genes (Beclin-1, Atg5) inhibit the formation of human breast tumors in mouse models." (PMID 28930154, 2017). "Basal-like breast tumors were seen in 42.0% of patients who had low BECN1 but high BRCA1 expression but in only 0.7% of patients who had high BECN1 but low BRCA1 expression (P = 9.05E− 17 for the difference between groups)." (PMID 25825707, 2015). "Basal-like breast tumors were seen in 31.0% of patients who had low BECN1 but high BRCA1 expression but in only 4.3% of patients who had high BECN1 but low BRCA1 expression (P = 3.39E − 24 for the difference between groups)." (PMID 25825707, 2015). "Inactivation of autophagy-specific genes, including Beclin-1, results in increased tumorigenesis in mice, and enforcement of the expression of such genes inhibits the formation of human breast tumors in mouse models." (PMID 25202355, 2014). "We studied the expression of beclin 1 and explored the possible regulatory mechanisms on its expression in breast tumors." (PMID 20230646, 2010). "There was significant positive correlation between beclin 1 mRNA expression and immunoreactivity in breast tumors (p < 0.001)." (PMID 20230646, 2010). "We detected relative mRNA expression of beclin 1 of 20 breast tumor tissues vs. corresponding normal tissues by quantitative RT-PCR." (PMID 20230646, 2010). "We found that certain CpG dinucleotides at the promoter and the intron 2 of the beclin 1 gene are hypermethylated in breast tumors." (PMID 20230646, 2010). "Decreased beclin 1 mRNA expression was detected in 70% of the breast tumors, and the protein levels were co-related to the mRNA levels." (PMID 20230646, 2010). "In the present study, we showed that the mRNA and protein expression of beclin 1, another 17q21 gene, was frequently down-regulated in breast tumors." (PMID 20230646, 2010).
breast tumors (continued). "Moreover, enforced expression of Beclin-1 has been shown to inhibit the formation of human breast tumors in mouse models." (PMID 24885292, 2014). "Therefore, we first detected the methylation status of the CpG islands in the 6 breast tumors with significantly down-regulated beclin 1 expression and corresponding normal tissues by bisulfite sequencing." (PMID 20230646, 2010). "Although down-regulated expression with mono-allelic deletions of beclin 1 gene was frequently observed in breast tumors, whether there was other regulatory mechanism of beclin 1 was to be investigated." (PMID 20230646, 2010). "Furthermore, 6 out of 20 (30%) in the breast tumors showed a significant decrease (tumor: normal tissue ratio < 0.5) of beclin 1 mRNA expression." (PMID 20230646, 2010). "No mutation was found in 12 exons of the beclin 1 gene in 20 breast tumors." (PMID 20230646, 2010). "In human breast tumor tissues, the expression levels of Beclin-1 and ATG5 were significantly higher in stage I breast tumor tissues." (PMID 33806593, 2021). "In summary, BECN1 is found to be deleted independently of BRCA1 in some ovarian and breast tumors, although the majority delete BECN1 and BRCA1 concomitantly." (PMID 31923184, 2020). "BECN1 and BRCA1 were each deleted in approximately one-third of the breast tumors in both the TCGA and METABRIC datasets (BECN1 deletion in 34% in TCGA and 33% in METABRIC; BRCA1 deletion in 35% in TCGA and 27% in METABRIC)." (PMID 25825707, 2015). "Similar observations have been made in other breast tumor models by showing that CQ but not knockdown of Beclin 1 or ATG12 sensitized the tumor to chemotherapy." (PMID 29774126, 2018). "To ascertain whether there was a correlation between EHMT2 and Beclin-1 expression in cancer, we examined the expression levels of EHMT2 and Beclin-1 in breast tumor tissue by Western blotting." (PMID 27174920, 2016). "Then we tested another 6 cases, whose beclin 1 mRNA expression was not down-regulated in breast tumors, and methylation was weakly or hardly detected in both tumors and normal tissues." (PMID 20230646, 2010).
Stroke (24 papers, 2013 to 2025). Sudden impairment of blood flow to a part of the brain due to occlusion or rupture of an artery to the brain. "Therapeutic agents such as rapamycin, Tat-Beclin 1, and Urolithin A consistently demonstrated neuroprotection in preclinical stroke models." (PMID 41007413, 2025). "In one study of 37 stroke patients and 21 controls, the autophagy markers BECLIN-1 and LC3B were found to be correlated with initial NIHSS scores and functional outcomes defined by modified Rankin Scale scores and improvement in NIHSS scores at three months." (PMID 37446092, 2023). "ISO reduced LC3B and Beclin-1 expression after stroke, indicating that the production of autophagosomes was decreased." (PMID 35419168, 2022). "We found expressions of LC3-II and Beclin 1 obviously elevated in MCAo group compared with sham group (p < 0.001), showing stroke triggered autophagy." (PMID 34257822, 2021). "The results showed that the expression of LC3-II/LC3-I and Beclin-1 was significantly increased while P62 protein level was decreased after stroke model." (PMID 32698909, 2020). "Of note, immunofluorescence expansion of Beclin-1 was noted in both ipsi- and contralateral capillary endothelium of post-stroke animals, likely indicating autophagosome vacuole formation." (PMID 23675488, 2013). "Similarly, MALAT1 can also sponge miR-30a, releasing translational inhibition on Beclin-1, which promotes autophagosome formation and reduces neuronal apoptosis following stroke." (PMID 41007413, 2025). "The anti-apoptotic protein BCL2L1 binds with BECN1 as a suppressor of autophagy, while their expression changed in the opposite direction, indicating a more complicated situation of autophagy in CE stroke." (PMID 37305740, 2023). "Through bio-informatic analysis, we found that stroke related genes RhoB and beclin-1 might be the targets of miR-30a." (PMID 24237608, 2013). "Increased immunoreactivity of SIRT1, Beclin 1, ATG7, LC3-I/II, and cleaved caspase-3 was also noted in stroke brains." (PMID 40724883, 2025). "An increased expression of SIRT1 and proteins essential for autophagy, including Beclin 1, autophagy-related proteins ATG3, ATG5, ATG7, ATG12-5, and LC3-II/I, was observed postmortem in the brains of stroke patients." (PMID 40724883, 2025). "When mice were subjected to MCAO and treated with NSC-EVs or LBP-pretreated NSC-EVs, the stroke-induced increased protein abundance of LC3-II and Beclin-1 was reversed, accompanied by a decrease in P62 protein accumulation." (PMID 37691119, 2023). "The remaining autophagy-related genes, such as ATG12, ATG16L2, ATG2B, and BECN1 were also significantly increased in CE strokes while not all types of strokes." (PMID 37305740, 2023). "Notably, stroke-induced excessive autophagy was further inhibited by LBP-pretreated NSC-EVs, resulting in the expression reduction of Beclin-1 and LC3II, accompanied by an increased abundance of P62." (PMID 37691119, 2023). "The western blot results showed that the autophagy-related protein Beclin-1 was similar to NOX2 and ROS and significantly increased on Day 3 after stroke but gradually decreased between Day 3 and Day 14, and this effect was significantly inhibited by the NOX2 inhibitor apocynin." (PMID 35836200, 2022). "However, not all beclin-1 positive cells were caspase-3 positive, which indicated that not all the beclin-1 positive cells were predestined to die following stroke." (PMID 23688351, 2013).
lung adenocarcinoma (23 papers, 2011 to 2025). A carcinoma that arises from the lung and is characterized by the presence of malignant glandular epithelial cells. "A positive correlation (r = 0.6655, P = 0.0001) between BECN1 and circ_0020850 was confirmed in 37 cases of lung adenocarcinoma tissues." (PMID 35012553, 2022). "Together, these findings suggest that the USP5-Beclin 1 pathway plays a critical role in lung adenocarcinoma development." (PMID 36528652, 2022). "Next, we further investigated the relationship among circ_0020850, miR-326, and BECN1 in lung adenocarcinoma cell." (PMID 35012553, 2022). "In the current research, our results partially disclosed that circ_0020850 promotes the malignant behaviors of lung adenocarcinoma by regulating miR-326/BECN1 axis." (PMID 35012553, 2022). "The mRNA level of BECN1 was obviously upregulated, and it was negatively correlated (r = − 0.7107, P < 0.0001) with miR-326 expression in lung adenocarcinoma tissues (n = 37)." (PMID 35012553, 2022). "And it functions as an oncogene in lung adenocarcinoma, as BECN1 overexpression partly reversed the suppression effect on lung adenocarcinoma progression." (PMID 35012553, 2022). "For example, haploinsufficiency of Becn1/Beclin 1 in genetically modified mice resulted in tumor formation in various systems, including lung adenocarcinomas, HCCs, and heamatological malignancies." (PMID 28459042, 2017). "In summary, circ_0020850 knockdown inhibited migration, invasion, proliferation, and angiogenesis but stimulated apoptosis in lung adenocarcinoma cells, which might be dependent on miR-326/BECN1 networks and ceRNA mechanisms." (PMID 35012553, 2022). "Inconsistent with previous research, BECN1 was upregulated in lung adenocarcinoma tissues." (PMID 35012553, 2022). "Circ_0020850 promoted the malignant development of lung adenocarcinoma by regulating miR-326/BECN1 axis, indicating that circ_0020850 might serve as a promising target for the diagnosis and treatment of lung adenocarcinoma patients." (PMID 35012553, 2022). "Therefore, circ_0020850 upregulated BECN1 expression by sponging miR-326 in lung adenocarcinoma cells." (PMID 35012553, 2022). "Similarly, the protein level of BECN1 was obviously upregulated in lung adenocarcinoma tissues and cells." (PMID 35012553, 2022). "Herein, we found that BECN1 is a target of miR-326 in lung adenocarcinoma." (PMID 35012553, 2022). "Hence, miR-326 mediated the malignant behaviors of lung adenocarcinoma cells by regulating BECN1." (PMID 35012553, 2022). "Additionally, miR-326 could negatively regulate BECN1 expression, thereby regulating lung adenocarcinoma cell phenotypes." (PMID 35012553, 2022). "In addition, we found that circ_0020850 could upregulate BECN1 expression by sponging miR-326 in lung adenocarcinoma." (PMID 35012553, 2022). "Similarly, an mRNA expression database (containing 440 lung adenocarcinoma cases) for pro-autophagy markers was queried and the results showed that high expression of BECN1, ATG12, and DRAM1 are closely linked to increased survival among lung adenocarcinoma patients." (PMID 31101821, 2019). "Beclin-1 expression was negatively correlated with tumor size and tumor stage of lung adenocarcinoma, and Beclin-1 expression was decreased in NSCLC tissues compared with normal tissues." (PMID 36178365, 2022). "Moreover, at the post-transcriptional level, circular RNA G6PC3 was found to promote lung adenocarcinoma progression by physically binding to both HMGB1 and Beclin 1, thereby stabilizing their interaction and enhancing the formation of the pro-autophagic HMGB1/Beclin 1 complex." (PMID 41465435, 2025). "However, whether circ_0020850/miR-326/BECN1 axis mediated the progression of lung adenocarcinoma by regulating autophagy has not been explored." (PMID 35012553, 2022).
cardiac hypertrophy (22 papers, 2012 to 2025). "However, it is not known whether miR-30a can influence autophagy in cardiomyocytes through regulation of beclin-1 gene expression, and whether excessive autophagy mediates the actions of Ang II to cause myocardial hypertrophy." (PMID 23326547, 2013). "A few exceptions include that Tat-BECN1 increases unexpected synovial hyperplasia and cardiac hypertrophy; it intensifies brain damage after cerebral ischemic stroke." (PMID 36172279, 2022). "We found that LC3II and Beclin-1 protein expression was markedly increased in PE-induced cardiac hypertrophy, while p62 protein expression was significantly decreased." (PMID 33240671, 2020). "Simultaneously, forcing overexpression of miR‐103 in neonatal rat ventricular myocytes dramatically inhibited mark proteins BNP and β‐MHC (cardiac hypertrophy), and Beclin‐1 and LC3‐II expressions, as well as autophagic flux activation (cardiac autophagy)." (PMID 30604587, 2019). "In the present study, we showed that rapamycin attenuates cardiac hypertrophy by inducing autophagy and elucidated a potential underlying mechanism involving MEK/ERK12 signaling and the modulation of the expression of Noxa and Beclin-1." (PMID 27047390, 2016). "Taken together, our results indicate that rapamycin attenuates cardiac hypertrophy by promoting autophagy through a mechanism involving the modulation of Noxa and Beclin-1 expression by the MEK/ERK signaling pathway." (PMID 27047390, 2016). "Here, we showed that rapamycin had a protective effect against cardiac hypertrophy and elucidated a potential underlying mechanism mediated by the induction of autophagy via MEK/ERK dependent up-regulation of Beclin-1 and Noxa." (PMID 27047390, 2016). "Based on these observations, we propose that beclin-1 gene over-expression and excessive autophagy mediate Ang II-induced myocardial hypertrophy." (PMID 23326547, 2013). "Angiotensin II-induced myocardial hypertrophy was found to be mediated by over-expression of the beclin-1 gene." (PMID 23326547, 2013). "Tat-BECN1 not only reduces apoptosis but enhances proliferation in synovial intima cells leading to synovial hyperplasia in mouse knee joints; it augments cardiac hypertrophy in autosomal dominant polycystic kidney disease mouse model." (PMID 36172279, 2022). "Beclin1 and Atg5 are two autophagy-related (Atg) proteins, however they show a different result between Becn1+/− mice with alleviative myocardial remodeling and Atg5+/− mice with aggravating myocardial hypertrophy in pathological myocardial remodeling." (PMID 35534453, 2022). "On the contrary, Beclin-1 overexpression or some pharmacological agonists aggravated cardiac hypertrophy by activating autophagy, which implied that excessive autophagy may give cell death and act as an undesirable role in maintain cardiac function." (PMID 34749750, 2021). "In addition, pretreatment with Tat-Beclin-1 (a mitophagy inducer) reduced myocardial hypertrophy and diastolic dysfunction induced by continuous high-fat diet feeding." (PMID 33859776, 2021). "Therefore, the expression levels of LC3, Beclin-1 and p62 can reflect the autophagy in cardiac hypertrophy." (PMID 33240671, 2020). "It has been found that LC3, Beclin-1 and p62 are key regulators of autophagy, and reversion of their expression could attenuate cardiac hypertrophy." (PMID 33240671, 2020). "TRPV3 protein, cardiac hypertrophy marker proteins (BNP and β‐MHC) and autophagy associated proteins (Beclin‐1 and LC3‐II) were up‐regulated, as well as, miR‐103 expression and autophagy associated proteins (p62) were down‐regulated in cardiac hypertrophy models in vivo and in vitro respectively." (PMID 30604587, 2019). "We found that silencing of the beclin-1 gene by RNA interference caused decreased expression of genes related to myocardial hypertrophy, whereas over-expression of the beclin-1 gene resulted in an enhancement of the expression of genes related to myocardial hypertrophy." (PMID 23326547, 2013).
cardiac hypertrophy (continued). "We were interested in determining whether over-expression of the beclin-1 gene and excessive autophagy are mechanisms that mediate Ang II-induced myocardial hypertrophy." (PMID 23326547, 2013). "Inhibiting SLC26A4 displayed enhanced autophagy indicated by lower beclin-1 and LC3II/I and higher P62 in PE-induced cardiac hypertrophy." (PMID 31998553, 2020).